ISCA1 (iron-sulfur cluster assembly 1)
Description:
Involved in the maturation of mitochondrial 4Fe-4S proteins functioning late in the iron-sulfur cluster assembly pathway. Probably involved in the binding of an intermediate of Fe/S cluster assembly.
Synonyms: hIscA; HBLD2; MGC4276; ISA1; hIscA1; MMDS5
Tractability: PROTAC: its protein half-life has been measured.
Gene: Protein-coding gene on chromosome 9 (86,264,546 to 86,283,102, reverse strand). Ensembl gene ENSG00000135070.
Subcellular location: Mitochondrion
Pathways (Reactome):
Metabolism: Maturation of TCA enzymes and regulation of TCA cycle; Mitochondrial iron-sulfur cluster biogenesis
Gene Ontology:
Molecular function: protein binding; 2 iron, 2 sulfur cluster binding; iron-sulfur cluster binding
Biological process: protein maturation; iron-sulfur cluster assembly
Cellular component: iron-sulfur cluster assembly complex; mitochondrial [4Fe-4S] assembly complex; mitochondrion; cytoplasm; mitochondrial matrix
Genetic constraint (gnomAD): Loss-of-function variants: 5 observed, 5.17 expected, observed/expected ratio (o/e) 0.97, 90% interval 0.5 to 1.78. That is too few expected variants to judge how well the gene tolerates losing a copy. Missense variants: 62 observed, 75.56 expected, observed/expected ratio (o/e) 0.82, 90% interval 0.67 to 1.01. Synonymous variants: 24 observed, 25.18 expected, observed/expected ratio (o/e) 0.95, 90% interval 0.69 to 1.34.
Homologues: Orthologues: dog ISCA1 (98% identical), mouse Isca1 (97% identical), rat Isca1 (97% identical), mouse AK157302 (96% identical), tropical clawed frog isca1 (88% identical), macaque ISCA1 (84% identical), zebrafish isca1 (84% identical), Drosophila melanogaster MagR (76% identical), Caenorhabditis elegans Y39B6A.3 (64% identical). Paralogues in human: ISCA2 (28% identical).
Diseases named in the same sentence as ISCA1 in open-access papers:
ISCA1 is named in the same sentence as 16 diseases in open-access papers, as found by Europe PMC text mining. Sharing a sentence is not in itself a finding about the gene and the disease. The quoted sentences say what the papers report.
multiple mitochondrial dysfunctions syndromes (3 papers, 2018 to 2021). "Defects in several proteins involved in the biosynthesis and trafficking of [4Fe-4S] clusters are associated with multiple mitochondrial dysfunctions syndromes (MMDS), with NFU1 causing MMDS1, BOLA3 causing MMDS2, IBA57 causing MMDS3, ISCA2 causing MMDS4, and ISCA1 causing MMDS5." (PMID 32151725, 2020). "The methodology we have adopted was based on Pubmed searches using “multiple mitochondrial dysfunction syndrome”, “NFU1”, “BOLA3”, “IBA57”, “ISCA2”, and “ISCA1” as keywords." (PMID 34440194, 2021). "Defects in ISCA1, ISCA2 and IBA57 have been associated with numerous mitochondrial diseases now categorized as multiple mitochondrial dysfunctions syndromes MMDS3 (IBA57), MMDS4 (ISCA2), and MMDS5 (ISCA1)." (PMID 30200358, 2018).
anemia (1 paper, 2021). A reduction in the number of red blood cells, the amount of hemoglobin, and/or the volume of packed red blood cells. "Moreover, it was found that knockdown of the IscA1 led to anemia in zebra fish (Nilsson, Schultz & Pierce, 2009)." (PMID 34760372, 2021).
cardiomyopathy (1 paper, 2021). A disease of the heart muscle or myocardium proper. "Therefore, our findings are consistent with the mitochondrial damage and cardiomyopathy phenotypes found in clinical patients with Isca1 mutations." (PMID 34977489, 2021).
dilated cardiomyopathy (1 paper, 2021). Cardiomyopathy which is characterized by dilation and contractile dysfunction of the left and right ventricles. "Isca1 HET rats exhibited dilated cardiomyopathy characteristics, including thin‐walled ventricles, larger chambers, cardiac dysfunction and myocardium fibrosis." (PMID 34977489, 2021). "In this study, a myocardium specific Isca1 knockout heterozygote rat model was established that exhibited the typical MMDS pathological phenotype of dilated cardiomyopathy (DCM) and complex mitochondrial damage to both the structure and function of the myocardium." (PMID 34977489, 2021).
kidney cancer (1 paper, 2022). Primary or metastatic malignant neoplasm involving the kidney. "In our research, we found that NFU1, ISCA1, ISCA2, C1ORF69, and BLOA3 were altered significantly in kidney cancer tissues in multiple datasets." (PMID 36385109, 2022).
liver cancer (1 paper, 2024). An epithelial or non-epithelial malignant neoplasm that arises from the liver. "This situation exists in a wide range; for example, after knocking down the gene in hepatitis B virus S gene, chicken liver cancer cell lines LMH VNN1 gene, and early rat embryos ISCA1 gene, the expression of knockdown proteins can still be detected by Western blot." (PMID 38203840, 2024).
multiple mitochondrial dysfunctions syndrome 1 (1 paper, 2022). Any fatal multiple mitochondrial dysfunctions syndrome in which the cause of the disease is a mutation in the NFU1 gene. "In human, mutations in NFU1, BOLA3, IBA57, ISCA2, and ISCA1 genes lead to Multiple Mitochondrial Dysfunctions Syndromes 1 to 5 (MMDS1 to MMDS5) respectively." (PMID 35677241, 2022).
renal clear cell carcinoma (1 paper, 2022). "More importantly, the results of immunohistochemistry showed that the expression of NFU1, ISCA1, ISCA2 and C1ORF69 in normal tissues was higher than that in renal clear cell carcinoma tissues." (PMID 36385109, 2022). "The results of immunohistochemistry showed that the expression levels of NFU1, ISCA1, ISCA2 and C1ORF69 in normal tissues were higher than those in renal clear cell carcinoma tissues, which further verified our previous hypotheses." (PMID 36385109, 2022).
thyroid carcinoma (1 paper, 2024). "Our systematic analysis suggested that ISCA1 could serve as a predictive biomarker for prognosis and response to tumor immunotherapy in thyroid carcinoma (THCA) patients." (PMID 39766805, 2024). "Our findings revealed that ISCA1 could serve as a biomarker in thyroid carcinoma, play a role with different FRGs in various cell types, and mediate different ligand–receptor pathways for cell–cell communication." (PMID 39766805, 2024).
tumor (6 papers, 2020 to 2024). "Therefore, we concluded that the poor prognosis of high expression of ISCA1 can be linked to this tumor immunosuppressive microenvironment." (PMID 36072584, 2022). "Some studies suggest the potential involvement of ISCA1 in tumor progression through interactions with ferroptosis-related genes (FRGs) and the tumor immune microenvironment (TME)." (PMID 39766805, 2024). "We found that ISCA1 RNA was positively correlated with all six tumor stemness features in TGCTs and was positively correlated with DMPs, DNAss, ENHss, and EREG.METH in PCPGs but was negatively correlated with BLCA and BRCA." (PMID 39766805, 2024). "We aimed to uncover the potential connection between ISCA1 and ferroptosis in killing tumor cells across various types of cancer." (PMID 39766805, 2024). "Iron supplementation or ectopic expression of SDHB or ISC assembly 1 (ISCA1) can improve mitochondrial defects and promote tumour progression." (PMID 38853203, 2024). "Using the difference analysis, it was discovered that the expression of the ISCA1 gene in BLCA tumor samples was decreased in comparison to that in adjacent samples." (PMID 36072584, 2022). "We used the UALCAN database to analyze ISCA1 protein levels between normal and tumor tissues." (PMID 39766805, 2024). "Finally, the first pan-cancer investigation of ISCA1 indicated that the factor was differently expressed between tumor and normal tissues, as well as a link between ISCA1 expression and BLCA clinical outcome." (PMID 36072584, 2022). "Moreover, we delineated the potential functions of ISCA1 and its impact on ferroptosis-related genes (FRGs), immune regulatory genes (IRGs), immune checkpoint genes (ICGs), immune cell infiltration, tumor stemness, and genomic heterogeneity at the pan-cancer level." (PMID 39766805, 2024). "ISCA1 may alter tumor-infiltrating immune cells, which could be majorly involved in tumor immunity." (PMID 36072584, 2022). "We evaluated the expression differences of ISCA1, ISCA2, C1ORF69 and NFU1 normal tissues versus tumor tissues and among tumor tissues of KIRC." (PMID 36385109, 2022). "There were significant differences in the mRNA expression levels of ISCA1, ISCA2, C1ORF69 and NFU1 in KIRC among different tumor grades and individual cancer stages." (PMID 36385109, 2022). "Moreover, there were significant differences in the mRNA expression levels of ISCA1, ISCA2, C1ORF69 and NFU1 in KIRC among different tumor grades and individual cancer stages." (PMID 36385109, 2022). "In addition, we also analyzed the expression of NFU1, ISCA1, ISCA2, C1ORF69 and BLOA3 genes in various tumor types through the oncomine database." (PMID 36385109, 2022). "The results showed that the expression levels of ISCA1, ISCA2, C1ORF69 and NFU1 were significantly different in normal tissues versus KIRC tumor tissues (p < 0.01), among different tumor grades (p < 0.01), and among different individual cancer stages (p < 0.01)." (PMID 36385109, 2022).
cancer (3 papers, 2022 to 2024). A tumor composed of atypical neoplastic, often pleomorphic cells that invade other tissues. "If ISCA1 is dysregulated, it could potentiate the dysregulation of iron and oxidative homeostasis, thus increasing or decreasing the susceptibility of cancer cells to ferroptosis, depending on the nature of the disruption." (PMID 39766805, 2024). "Furthermore, whereas ISCA1 expression was linked to both immunological and clinical survival in human cancer, it was unclear whether ISCA1 affected clinical survival via the immune pathway." (PMID 36072584, 2022). "Overall, the RNA expression of ISCA1 was positively related to the infiltration of NK cells, neurons, and smooth muscle cells but negatively correlated with that of other cells in most cancer types." (PMID 39766805, 2024). "We examined the differential expression of the ISCA1 gene and transcripts in normal and cancer tissues." (PMID 39766805, 2024). "In this study, we employed public databases to examine the RNA expression, copy number variation (CNV), and methylation levels of ISCA1 across various cancer types." (PMID 39766805, 2024). "We conducted a detailed analysis of the genomic aberrations and CNVs of ISCA1 across various cancer types." (PMID 39766805, 2024). "The results revealed that ISCA1 CNV was positively correlated with TGFBR1 RNA expression in most cancers, and ISCA1 methylation was correlated with the RNA expression levels of these 33 immune genes in COAD, LIHC, and TGCT." (PMID 39766805, 2024). "ISCA1 inhibits the proliferation of THCA cancer through the interaction of TRGs with the immune microenvironment." (PMID 39766805, 2024). "Collectively, our findings provide a comprehensive perspective on the regulatory functions of ISCA1 and FRGs across various cancer types, potentially offering new insights for the development of novel therapeutic strategies." (PMID 39766805, 2024). "Among the 49 FRGs, HSPB1 was the only gene that was negatively correlated with ISCA1 in most cancer types." (PMID 39766805, 2024). "First, while bioinformatics analysis supplied us with some useful information on ISCA1’s role in cancer, we still needed in vitro or in vivo biology experiments to confirm our findings and boost therapeutic use." (PMID 36072584, 2022). "Research has suggested that the ISCA1 gene is downregulated in 11 types of cancer and upregulated in 4 cancer types." (PMID 36072584, 2022). "As a result, we sought to investigate ISCA1’s predictive value in 33 cancer types as well as its possible immunological function." (PMID 36072584, 2022). "Overall, our outcomes indicated that ISCA1 is involved in the progression of pan-cancer, particularly in BLCA." (PMID 36072584, 2022). "The expression level of ISCA1 in different forms of cancer and its connection with prognosis were studied using two databases: TCGA and Gene Expression Omnibus (GEO)." (PMID 36072584, 2022). "The outcomes indicated that: among the 24 tumors with para-cancerous samples, the expression of the ISCA1 gene in 15 cancer species was considerably varied in comparison to that in para-cancerous samples." (PMID 36072584, 2022). "When we analyzed the correlation between ISCA1 CNV, methylation and RNA levels, we found that the CNV of ISCA1 was positively correlated with RNA expression in most cancer types, whereas the methylation levels of ISCA1 were negatively related to RNA expression in most cancer types." (PMID 39766805, 2024). "Alterations in ISCA1 could theoretically impact the availability of iron for processes necessary for ferroptosis, thus affecting cancer cell vulnerability to this cell death mechanism." (PMID 39766805, 2024). "Compared with other cancers, ISCA1 was more closely related to these 33 immune genes in UVM." (PMID 39766805, 2024). "The link between these four gene types with ISCA1 was varied in various types of cancer." (PMID 36072584, 2022). "Further research into the involvement of ISCA1 in each cancer is required." (PMID 36072584, 2022).
cancer (continued). "Moreover, the link between CTLA4, PDCD1, CD86, CD274, and ISCA1 in various cancer types was measured." (PMID 36072584, 2022). "The Spearman correlation between these genes and the ISCA1 was measured in pan-cancer." (PMID 36072584, 2022). "ISCA1 can be a prognostic marker for a variety of cancers, particularly BLCA." (PMID 36072584, 2022). "Moreover, the ISCA1 gene expression in pan-cancer was observed." (PMID 36072584, 2022). "We also calculated the relationships between the methylation levels of ISCA1 and FRG RNA expression in multiple cancer types, and the results revealed that ISCA1 methylation was negatively correlated with most of these 49 FRGs in BLCA and PAAD." (PMID 39766805, 2024). "We subsequently investigated the correlations between the CNV of ISCA1 and the RNA expression of FRGs and reported that the ISCA1 CNV was positively correlated with TSC1, FXN, BRD3, and MAPKAP1 in most cancer types." (PMID 39766805, 2024). "Although there is some evidence that ISCA1 gene expression impacts energy metabolism and consequently has a role in tumorigenesis and cancer metastasis in different types of malignancies, no systematic pan-cancer study of the ISCA1 has been conducted." (PMID 36072584, 2022).
infection (2 papers, 2017 to 2025). The state of being infected such as from the introduction of a foreign agent such as serum, vaccine, antigenic substance or organism. "Fifteen days post-infection, a strong acidification of the medium (yellow colour) was observed in the culture infected with Isca1 shRNA, suggesting that ISCA1-depleted neurons are highly glycolytic and produce high levels of lactic acid due to mitochondrial dysfunction." (PMID 28492233, 2017).
ISCA1 also shares sentences with these, for which no sentence is quoted: hematological disease (1 paper); ischemic cardiomyopathy (1); mitochondrial disease (1); mitochondrial dysfunctions (1).